EGFR (epidermal growth factor receptor)
Diseases named in the same sentence as EGFR in open-access papers (continued):
Sharing a sentence is not in itself a finding about the gene and the disease.
lung cancer (continued). "Some clinical trials included only EGFR wild type lung cancers, others included only EGFR positive cases or a combination of wild type and positive cases." (PMID 37568643, 2023). "METTL3 plays a key role in the proliferation, survival, and invasion of lung cancer cells by promoting the expression of epidermal growth factor receptor (EGFR) and TAZ (a Hippo pathway effector)." (PMID 38072944, 2023). "This critical role of EGFR upregulation in the development, progression, and longevity of lung cancer has led to the development of drugs that control EGFR activity and expression." (PMID 37601068, 2023). "In terms of the miRNA-mRNA association, miR-140 has been reported to suppress invasive and angiogenic properties by altering EGFR levels in lung cancer." (PMID 37316916, 2023). "As mentioned, gefitinib, erlotinib, lapatinib, dacomitinib, and osimertinib are EGFR inhibitors received approval for non–small cell lung cancer (NSCLC) treatment." (PMID 38264122, 2023). "Although MIG6’s role in shielding EGF–induced mutant EGFR internalization remains debated, its undisputed function in preserving EGFR stability in lung cancer cells is evident." (PMID 37834326, 2023). "Among miRNAs involved in the pathogenesis and response to therapy of lung cancer, there is miR-153-3p, a molecule lowly expressed in these cases of nonsmall-cell lung cancer resistant to the epidermal growth factor receptor (EGFR) tyrosine kinase inhibitor." (PMID 37511303, 2023). "Collectively, these data suggest that mutant EGFR TL induces MUC1/MUC1-CT expression in lung cancer tissues." (PMID 36810913, 2023). "In the treatment of lung cancer, tyrosine kinase inhibitors (TKIs) targeting epidermal growth factor receptor (EGFR) have been widely used." (PMID 36765712, 2023). "EGFR and Kirsten rat sarcoma viral oncogene (KRAS) mutations are the two most common changes found in genetic diagnosis of lung cancer patients." (PMID 37576883, 2023). "SOX2 is a downstream target of GLI1, and the GLI1/SOX2 axis contributes to stemness-related EGFR resistance in lung cancer cells." (PMID 37149646, 2023). "In particular, LC_08PE patient had showed partial response (PR) to afatinib, an EGFR-targeted drug, after the lung cancer diagnosis, leading to the disappearance of almost all the tumors." (PMID 37993887, 2023). "Previous studies showed that CPNE1 is a critical factor in the tumorigenesis of lung cancer and that its mechanism involves the EGFR signaling pathway." (PMID 37077419, 2023). "Some of the RTKs that were highly expressed in lung cancer cell lines are the Epidermal growth factor receptor (EGFR), fibroblast growth factor receptor 1 (FGFR1), insulin-like growth factor 1 receptor (IGF1R), and tyrosine-protein kinase Met (MET)." (PMID 36926328, 2023). "Adding NTS to lung cancer cells increases the shedding of TGFα, which activates the EGFR, or neuregulin-1, which activates HER3." (PMID 37508387, 2023). "In lung cancer patients, Ceograph detects elongated tumor nuclei and diminished stroma-stroma closeness as biomarkers for insensitivity to EGFR tyrosine kinase inhibitors." (PMID 37461694, 2023). "EGFR is well known to play diverse roles in tumorigenesis, proliferation, survival, and metastasis in many human malignancies including lung cancer." (PMID 37487081, 2023). "Recent studies have shown that the signal of focal adhesion is decreased in tumors of patients with lung recurrence, while up to 75.8% of all lung cancer patients with first distant metastases have EGFR‐positive or HER2‐positive." (PMID 37688399, 2023). "Since adenocarcinomas represent at most 50% of all lung cancers worldwide, EGFR mutant lung adenocarcinomas will represent <7% of all lung cancers." (PMID 37169023, 2023). "Gefitinib (GEF) is a clinical medication for the treatment of lung cancer targeting the epidermal growth factor receptor (EGFR)." (PMID 38140054, 2023).
lung cancer (continued). "Reduced levels of FUT7 CpG DNA methylation have been found in lung cancer, especially in LUSC, and FUT7 promotes lung cancer proliferation by activation of the EGFR/AKT/mTOR signal pathway." (PMID 37256139, 2023). "Here, using preclinical mouse models and clinical datasets, we showed that T cell activation is important for the response of EGFR-mutant lung cancers to osimertinib." (PMID 36817465, 2023). "In contrast, the effect of multi-target inhibitors is superior to that of EGFR single-target inhibitors for cancer treatment, suggesting that multi-target inhibitors be further explored for lung cancer treatments." (PMID 36903369, 2023). "These require local validation and implementation for clinical diagnostic purposes, similar to what has been previously done for several other actionable mutations in different tumor types (e.g., EGFR in lung cancer, BRAF in melanoma and lung cancer, etc.)." (PMID 36825198, 2023). "Epidermal growth factor receptor tyrosine kinase inhibitors (EGFR-TKIs), which are frequently employed in molecular targeted therapy for lung cancer, have demonstrated good performance." (PMID 38169723, 2023). "Recombinant HB-EGF reduced the sensitivity of ALK-rearranged lung cancer cells to lorlatinib, whereas EGFR knockdown restored the sensitivity of A925L and H2228 cells to lorlatinib in the presence of HB-EGF." (PMID 36702855, 2023). "Treatment history was available in eight patients with lung cancer and target therapies against EGFR and ERBB2 were administrated." (PMID 36325957, 2023). "Recently, AKR1B1 has been found to promote glutathione de novo synthesis to enhance acquired resistance to EGFR-targeted therapy in lung cancer." (PMID 36816947, 2023). "The correlation between PM2.5 and EGFR-driven lung cancer incidence was still significant (r = 0.38; P = 0.033) after this exclusion." (PMID 37020004, 2023). "The cytotoxicity and cellular uptake of NmAb-functionalized AuNPs are more efficient in skin cancer A431 cells (EGFRmedium) compared to lung cancer A549 cells (EGFRlow), very likely due to the different amounts of EGFR expression and cellular uptake." (PMID 37623652, 2023). "In contrast, transcriptome analysis and siRNA library showed that diverse epigenetic mechanisms intricately affect the adaptive resistance in ALK-rearranged lung cancer, indicating that EGFR is involved in part of the adaptive response to lorlatinib." (PMID 36702855, 2023). "In lung cancer, one gene that is not only highly expressed within lung cancers but is also expressed within pre-neoplastic lesions is the epidermal growth factor receptor (EGFR)." (PMID 37444523, 2023). "To further uncover the underlying molecular regulatory network involved in HFD-induced lung cancer progression, we tried to construct the signaling networks based on NF-κB signaling, EGFR and the significantly altered genes in our cDNA array." (PMID 37929799, 2023). "This is in line with a prior study that correlated EGFR aberrations with favorable tyrosine kinase inhibitor treatment outcomes in lung cancer." (PMID 37314501, 2023). "Meanwhile, several studies have demonstrated an enrichment of IFN antiviral defence pathway signalling in EGFR-mutant lung cancer DTCs treated with targeted therapy or chemotherapy." (PMID 37483492, 2023). "Recent reports suggested combining ramucirumab with epidermal growth factor receptor (EGFR)-tyrosine kinase inhibitors (TKIs) to overcome EGFR resistance in non–small cell lung cancer (NSCLC)." (PMID 37158884, 2023). "The relative rates of EGFR-driven lung cancer incidence (per 100,000 population), per 1 μg m−3 increment of PM2.5 levels were 0.63 (P = 0.0028) in England, 0.71 (P = 0.0091) in South Korea and 1.82 (P = 4.01 ×10−6) in Taiwan." (PMID 37020004, 2023).
lung cancer (continued). "Our results revealed that short‐term exposure to PM2.5 for 24 h indeed activated the EGFR pathway in lung cancer cells." (PMID 36975376, 2023). "Utilizing confocal microscopy, we established in human lung cancer cell lines harboring mutant or amplified EGFR that high level of GRP78 was readily observed in the perinuclear region typical of the ER as well as inside the nucleus." (PMID 37487081, 2023). "Established small‐molecule tyrosine kinase inhibitors (TKIs) target epidermal growth factor receptor (EGFR) and are effective in non‐small cell lung cancer (NSCLC) patients with activating and sensitizing EGFR mutations." (PMID 36621830, 2023). "In this study, we established a radiogenomic model on the basis of 18F-FDG PET/CT radiomics and clinical EGFR to predict the PFS stratification of lung-cancer patients after SBRT treatment." (PMID 37109413, 2023). "Although there is no consensus on the effects of betablocker treatment, it is interesting to note the role of β-ARs in lung cancer primarily have been linked to ADC- and EGFR-driven mutations, as reviewed elsewhere." (PMID 37696458, 2023). "In recent years, patients with advanced lung cancer now have much better survival owing to using epidermal growth factor receptor tyrosine kinase inhibitors (EGFR-TKIs), ushering in a new era of individualized therapy for lung adenocarcinoma." (PMID 37390230, 2023). "We found uncommon complex mutations (rare + rare) occur in 36.5% of rare EGFR mutations and 6.7% of all EGFR mutations in the GENIE lung cancer dataset." (PMID 36830579, 2023). "AP-MS also provides a system view of EGFR-PPI, including a 14-protein core network crucial for cell viability in multiple EGFR-mutated lung cancer cells, and a protein phosphatases interactome to clarify EGFR signaling." (PMID 37495186, 2023). "The results indicated that age ≥ 65 years, pretreatment KPS score ≤ 70, the ALK/EGFR wild type, and extracranial metastases were related to poor prognosis in patients with lung cancer BMs." (PMID 36826133, 2023). "Afatinib is an irreversible epidermal growth factor receptor (EGFR) tyrosine kinase inhibitor (TKI) used to treat patients with advanced EGFR-mutant lung cancer." (PMID 37046679, 2023). "cBioPortal analysis of mutation hotspots shows that EGFR mutations in GBM are most frequently found within the extracellular furin-like domain, while EGFR mutations in lung cancer typically occur within the intracellular kinase domain." (PMID 37457379, 2023). "Although the mortality rate from lung cancer is decreasing over the years, the identification of “druggable” oncogenes (such as EGFR, ALK) provides the opportunity for the study and implementation of effective targeted therapy." (PMID 37373500, 2023). "We provide clear evidence that 8PN treatment attracts neutrophils and triggers necrotic lung cancer cell death to effectively overcome EGFR TKI resistance." (PMID 37013960, 2023). "In lung cancer, epithelial growth factor receptor (EGFR) mutant tumor cells have been shown to express high levels of CD73, which give rise to high concentrations of immunosuppressive adenosine in the TME." (PMID 37180110, 2023). "Rapid activation of Notch3 is found in EGFR‐mutant lung cancer after EGFR TKI therapy, leading to an enhancement in β‐catenin activation and stability, which facilitates DTC survival." (PMID 37638338, 2023). "EGFR upregulation plays an important role in lung cancer as a well-established target for lung cancer therapy." (PMID 36831545, 2023). "More research is needed to identify the potential risks for lung cancer as well as the aspects related with a better outcome to EGFR-TKI." (PMID 36851259, 2023). "To exemplify how the PCN can be used to discover novel signaling responses, we considered pathway interactions with the EGF/EGFR signaling pathway, which has a well-established role in lung cancer." (PMID 36996232, 2023).
lung cancer (continued). "TMB, another predictive marker of immunotherapy, was found to be lower in EGFR‐mutant lung cancer than in lung cancer with wild‐type EGFR." (PMID 37699785, 2023). "Furthermore, in addition to the occurred resistance, EGFR TKIs are more associated with EGFR-activating mutations than wild-type EGFR (WT-EGFR), indicating that this strategy was of relatively little benefit to the majority of lung cancer patients with WT-EGFR." (PMID 37813845, 2023). "On the other hand, even in studies using lung cancer cell lines that are considered relatively homogeneous, EGFR-TKIs fail to eradicate all cancer cells." (PMID 36835536, 2023). "Previous studies have reported that ILF3 promoted lung cancer by activating the EGFR-mediated cellular pathway." (PMID 37337223, 2023). "Classical EGFR mutant lung cancer with exon 19 deletions, exon 21 L858R and de novo exon 20 T790M mutations are associated with good response to tyrosine kinase inhibitors." (PMID 36756152, 2023). "Increased EGFR activity was observed in esophagus cancers, glioblastoma, anal cancers, epithelial head and neck cancers, breast cancers and lung cancers." (PMID 36986673, 2023). "The mutation of RBM10 co-exists with the known lung cancer target genes KRAS, EGFR, and PIK3CA, among others." (PMID 37509501, 2023). "Studies reported that EGFR is overexpressed in cancer cells such as colorectal, breast, and non–small cell lung cancers." (PMID 37445686, 2023). "In 50-60% of NSCLC patients who developed resistance to first/second-generation TKIs, the occurrence of p.T790M in exon 20 of EGFR is a fixed point for lung cancer management." (PMID 37152062, 2023). "Overall, 1267 lung cancer cases were retrieved from TCGA which revealed a higher relative prevalence of EGFR (n = 30, 22.9% vs n = 148, 11.7%, P = 0.001) and CHEK2 (n = 11, 8.4% vs n = 20, 1.6%, P = 0.000001) mutations in the Northern England population." (PMID 37702806, 2023). "Because previous evidence showed that cytokine IL6 and IL8 secretion promoted necrosis in glioblastoma, we examined these two cytokines in lung cancer cells treated with 8PN or/and EGFR TKIs." (PMID 37013960, 2023). "This article presents the principle of lung cancer screening based on CYP1B1 gene polymorphism and polarization imaging and explores the diagnosis and treatment of non-EGFR mutant lung cancer." (PMID 37791062, 2023). "Our previous clinic data also suggested that the PIK3CA co-variation, accounting for 16.67% of EGFR-mutant lung cancer patients, was associated with poorer PFS, only 4.57 months, after EGFR-TKI treatment." (PMID 37553597, 2023). "High PD-L1 expression has been reported as an adverse predictor for treatment response in EGFR-positive lung cancer treated with EGFR-TKIs." (PMID 37958421, 2023). "For instance, CL-387,785 inhibits colony formation by lung cancer cells expressing an EGFR missense or deletion mutant more effectively than gefitinib and erlotinib, suggesting that CL-387,785 may be a good therapeutic for lung cancer with exon 20 insertion mutations of EGFR." (PMID 37601068, 2023). "ZEB proteins have been shown to protect lung cancer cells from EGFR-induced senescence through their ability to down-regulate CDKN1A and CDKN2B." (PMID 38069026, 2023). "Our data indicate that KAN0441571C in combination with EGFR or BTK inhibitors had synergistic apoptotic effects on lung cancer cells." (PMID 37111634, 2023). "Epidermal growth factor receptor (EGFR)-tyrosine kinase inhibitors (TKIs), such as osimertinib and gefitinib, have only been proven to be beneficial for patients with EGFR-sensitizing genetic alterations in lung cancer." (PMID 37627320, 2023). "That is, for patients with EGFR-mutant resected lung cancer, is the optimal adjuvant treatment modality EGFR-TKIs alone or a combination of EGFR-TKIs and chemotherapy?" (PMID 37528390, 2023).
lung cancer (continued). "Afatinib is an irreversible tyrosine kinase inhibitor (TKI) targeting the epidermal growth factor receptor (EGFR), which is utilized for the treatment of patients with advanced lung cancer that harbors EGFR mutations." (PMID 37046679, 2023). "We previously reported that OBP-301 induces autophagy-related cell death in human lung cancer cells by suppressing the EGFR expression." (PMID 37972012, 2023). "The majority of advances in the treatment of lung cancer have been made in the area of targeted therapies, with a particular focus on non-small cell lung cancer (NSCLC) patients with EGFR mutations." (PMID 37240224, 2023). "The emergence of L858R as a potential biomarker holds promise for predicting the responsiveness of lung cancer models to anti-EGFR therapy." (PMID 38273823, 2023). "And the histone deacetylase inhibitor vorinostat was reported to increase the sensitivity to EGFR-TKIs by inducing ferroptosis through reducing the expression of SLC7A11 (xCT) in lung cancer cells." (PMID 36926345, 2023). "In our subgroup analysis using PCR as the standardized detection method, the multivariate analysis revealed a significant association between EGFR mutations and the DFS/RFS of early-stage lung cancer patients." (PMID 37907475, 2023). "Non-small cell lung cancer (NSCLC) is the most common lung cancer diagnosis, among which epidermal growth factor receptor (EGFR), Kirsten rat sarcoma (KRAS), and anaplastic lymphoma kinase (ALK) mutations are the common genetic drivers." (PMID 36949948, 2023). "In 2022, we used NCI-H1650 cells, the primary human NSCLC, and HUVECs to construct a lung-on-a-chip platform for evaluating the response of lung cancer cells to epidermal growth factor receptor (EGFR)-targeted drugs." (PMID 38026900, 2023). "We analyzed the GENIE lung cancer dataset (GENIE Cohort v12.0-public, n = 153,834) and found that Ex19Del and L858R are found in 71.9% of NSCLCs with an EGFR mutation." (PMID 36830579, 2023). "Chromosome 3q amplification was found in squamous transformation tissues in osimertinib-resistant EGFR mutant lung cancers." (PMID 38093367, 2023). "Our recent studies in EGFR mutant lung cancer cell lines and murine head and neck cancer cells demonstrated a TKI-stimulated IFNγ transcriptional response accompanied by increased chemokine expression." (PMID 36739466, 2023). "Of note, the correlation between PM2.5 and EGFR-driven lung cancer incidence was still significant (r = 0.55, P = 0.019) after these exclusions." (PMID 37020004, 2023). "In a number of malignancies, including lung cancer, EGFR have been shown to be found in very high concentrations and also play an important role in angiogenesis, tumor formation, and progression." (PMID 37760616, 2023). "EGFR-TKIs are currently a widely used targeted therapy in the clinical treatment of lung cancer, which can effectively improve the prognosis of NSCLC patients with EGFR mutations." (PMID 37626047, 2023). "This study was aimed to investigate the molecular, clinical characteristics, and prognostic features of NF1 gene in EGFR mutant lung cancer patients." (PMID 35702826, 2023). "One promising target is the EGFR signaling pathway, which is frequently dysregulated in lung cancer and plays a critical role in cancer cell proliferation, migration, and survival." (PMID 37580790, 2023). "KDD was identified at a ratio of 0.097% in this cohort and the majority was in the EGFR gene and lung cancer." (PMID 36325957, 2023). "Preclinical studies have examined ER and EGFR simultaneously and have found that estrogen through its receptor can stimulate lung cancer cell proliferation, resistance to cell death, angiogenesis, and metastasis." (PMID 37700839, 2023). "With advances in precision medicine, strategic management approaches in the use of EGFR, especially for lung cancer-related metastasis in neuro-oncology, will continue to change." (PMID 37190312, 2023).